SULF2 (sulfatase 2)
Diseases named in the same sentence as SULF2 in open-access papers (continued):
Sharing a sentence is not in itself a finding about the gene and the disease.
cancer (42 papers, 2010 to 2026). A tumor composed of atypical neoplastic, often pleomorphic cells that invade other tissues. "Sulf-2 is expressed primarily by epithelial cancer cells, is oncogenic in many cancers, and is associated with poor survival outcomes." (PMID 37958342, 2023). "We found studies of 8 cancers (bladder, esophagus, head and neck, kidney, liver, lung, and pancreatic) showing significant association of SULF2 with survival but the impact is less uniform." (PMID 36428645, 2022). "Our study confirms the overexpression of SULF1 and SULF2 in various cancers, which is commonly associated with poor survival outcomes; the 6-O-endosulfatases emerge as interesting targets for cancer monitoring and therapeutic intervention." (PMID 36428645, 2022). "In a number of cancers, SULF2 upregulation is associated with more advanced disease and poorer patient outcome." (PMID 36589727, 2022). "Studies have identified SULF2 as an oncogenic effector whose upregulation is associated with poor prognoses in patients with various cancers." (PMID 34440158, 2021). "The association of SULF2 and overall survival corresponds to previous findings in various types of cancer." (PMID 26882224, 2016). "Sulf-2 therefore represents an interesting candidate as diagnostic and prognostic biomarkers, which are greatly needed, in particular for these cancers." (PMID 24459635, 2014). "SULF1 and SULF2 are overexpressed in various human cancer types and can be associated to progression and prognosis." (PMID 21599997, 2011). "This, however, differs from in vivo speculation of the Sulf2 enzyme having some pro-angiogenic activity in some cancers, although cancer angiogenic cells may also have some additional mutations modifying their normal cell signalling responses." (PMID 35409127, 2022). "SULF2 upregulation has been suggested to promote tumorigenesis through its action on HSPGs and SULF2 is considered to be a cancer-causing agent and a potential therapeutic target for several cancers." (PMID 27223083, 2016). "Sulf‐2 protein was present in both with an increase in KO environment (where we anticipate relative increase of cancer cells in proportion to CAF cells)." (PMID 41549062, 2026). "SCC35 is an HNSCC-derived cancer cell line with high invasive potential and high expression of SULF2." (PMID 38732216, 2024). "Heparan-6-O-endosulfatases Sulf-1 and Sulf-2 are secreted extracellular enzymes overexpressed in many types of cancer." (PMID 38825040, 2024). "We show that Sulf-2 knockout inhibits cancer cell invasion in a spheroid co-culture model and we identified a novel Sulf-2 inhibitor that, in the same model, limits cancer cell invasion." (PMID 37958342, 2023). "In this study, we focused on the contribution of Sulf-2, dominant in the cancer cells, to the local invasiveness of HNSCC cell lines in a spheroid co-culture model with primary HNSCC CAF." (PMID 37958342, 2023). "At the same time, we found that the secretome of HNCAF37, a primary HNSCC CAF, contains the Sulf-2 protein but in a lower amount (approximately half) compared to the cancer cell lines." (PMID 37958342, 2023). "The primary HNCAF37 cells are necessary for the cancer cell invasion but Sulf-2-KO in the cancer cells is sufficient to reduce the ability of the SCC35 and Cal33 cell lines to generate invadopodia and invade Matrigel." (PMID 37958342, 2023). "We therefore focused our study on the CAF-assisted invasiveness of the cancer cells, observed by us and others, and its dependence on the Sulf-2 enzyme." (PMID 37958342, 2023). "The cancer cell lines and CAF are all sources of the secretory Sulf-2 protein but the cancer cells contribute the majority of the enzyme." (PMID 37958342, 2023). "We observed >2-fold upregulation of both SULF1 and SULF2 mRNA in four cancer studies from the TCGA (HNSC, ESCA, LUSC, and STAD) and all these cancers remain significantly upregulated compared with the GTEX normal tissues." (PMID 36428645, 2022).
cancer (continued). "Based on the SULF expression in the two independent datasets (TCGA and CPTAC), we conclude that SULF1 is commonly upregulated across different cancer types while SULF2 overexpression is more restricted to certain cancer pathologies." (PMID 36428645, 2022). "The RNA sequencing results of cancer tissues of 90 patients showed that patients with MIBC had higher SULF2 expression than those with NMIBC (p = 0.003)." (PMID 36612128, 2022). "Sulfatase 2 (SULF2) affects the occurrence and development of cancer by regulating HSPG-binding factors." (PMID 36612128, 2022). "We have strong evidence that SULF1 is supplied by CAF while SULF2 is provided primarily by the cancer cells, which has important consequences because the secreted SULF enzymes act locally due to strong non-covalent interactions with cell surfaces." (PMID 36428645, 2022). "Proteogenomic analysis of the TCGA and CPTAC datasets conclusively documents a significant elevation of SULF1 and SULF2 in multiple cancer tissues compared with adjacent or normal counterparts." (PMID 36428645, 2022). "Elevated expression of SULF2 was detected in PDAC, and impairment of SULF2, obtained by silencing or by lentiviral shRNA-mediated inactivation, reduced cancer cell growth in vitro and in vivo by enhancing the Wnt pathway." (PMID 34249755, 2021). "Together, these findings suggest that dendrobine can be used as a radiotherapy efficiency enhancer, capable of significantly inhibiting IR-induced cancer cell invasion and metastasis by suppressing SULF2 mRNA and protein expression in vitro and in vivo." (PMID 34440158, 2021). "Although the roles of SULF2 in cancer development have been studied extensively, inhibitors targeting SULF2 remain less explored." (PMID 34440158, 2021). "Together with our previous findings, these results suggest that dendrobine inhibits IR-induced cancer cell migration and invasion by suppressing the mRNA and protein expression of SULF2, a key mediator of IR-induced signaling." (PMID 34440158, 2021). "SULF1 and SULF2 are dysregulated in a number of tumors, but their role in cancer progression is still controversial." (PMID 34249755, 2021). "Previous studies have reported that SULF2 regulates cancer progression by modulating the cell signaling pathways through two mechanisms." (PMID 33889573, 2021). "SOD2 was also essential for the invasion of un-irradiated cancer cells induced by upregulation of Bcl-XL, an intracellular oncogene, or extracellular factors, such as SULF2 and IL-6." (PMID 30755594, 2019). "These include genes already implicated in cancer metastasis and cancer signaling, like Wnt5A CTGF, SULF2, integrin B2." (PMID 29581836, 2018). "Many researchers also demonstrated the ability of SULF1 and SULF2 in editing post-synthetic sulfation status of 6-O-S from HSPGs, and thus the implication and potential roles of SULFs in malignancies were extensively investigated." (PMID 28525382, 2017). "SULF2 staining was localized to the cytoplasm of cancer cells; in addition, diffuse weak staining was observed in the extracellular stroma of the tissue of all categories and this background stain was not included in the IHC evaluation." (PMID 27223083, 2016). "Among the compounds described are the first relatively potent small molecule inhibitors of Sulf-2 that will aid further biological studies and assist elucidation of the role of Sulf-2 in cancer." (PMID 28660059, 2016).
cancer (continued). "SULF2 is of particular interest, as it is over-expressed in a range of cancers including hepatocellular, breast, pancreatic, non-small cell lung and esophageal carcinomas." (PMID 27223083, 2016). "Sulfatase 2 (SULF2), an extracellular sulfatase that alters sulfation on heparan sulfate proteoglycans, is involved in the tumorigenesis and progression of several carcinomas." (PMID 27223083, 2016). "DU-145 cancer cells overexpressing SULF2 showed 33.7% of cells double stained for WNT 3A and β-catenin respectively, in comparison to 20.7% in control cells transfected with empty vector." (PMID 25887999, 2015). "Alterations in SULF2 expression have been identified in the context of several cancer types but its function in cancer is still unclear where the precise molecular mechanism involved has not been fully deciphered." (PMID 25887999, 2015). "In support of this possibility, SULF2 was identified in an unbiased screen for upregulated genes in EMT transitions of cancer cells." (PMID 23950901, 2013). "In carcinoma cell lines, overexpression of SULF2 enhanced scratch-wound repair of monolayer cultures, whereas knockdown of endogenous SULF2 slowed the closing of scratch wounds in monolayers." (PMID 23950901, 2013). "The secretion of SULF1 and SULF2 raises the possibility for cancer cells to remodel the extra-cellular matrix in their environment, thereby affecting their development and/or the neighbouring host cells." (PMID 21599997, 2011). "Thus, we infer that LG3BP directly interacts with Sulf-2 and inhibits the Sulf-2-dependent cancer cell invasion." (PMID 38825040, 2024). "Furthermore, using in vitro enzymatic and cell culture assays, we showed that the interaction inhibits Sulf-2 enzymatic activity and modifies invasion of cancer cells into matrigel." (PMID 38825040, 2024). "Our results suggest that targeting Sulf-2 in HNSCC might be an interesting strategy to reduce local cancer cell invasiveness." (PMID 37958342, 2023). "The expressions of Sulf-1 and Sulf-2 is dysregulated in many cancers." (PMID 37958342, 2023). "This supports our hypothesis that Sulf-2 enzymatic activity promotes local invasion of the cancer cells." (PMID 37958342, 2023). "The HfFucCS could have additional mechanisms of action but we show clearly that it potently inhibits the Sulf-2 enzyme and blocks cancer invasion in a manner similar to the Sulf-2 knockout in the cancer cells." (PMID 37958342, 2023). "SULF2 is overexpressed in 8 cancer types of which 5 increase > 2-fold." (PMID 36428645, 2022). "Our PDX and RNA scope experiments confirm that SULF1 is provided to the tissues by cancer-associated fibroblasts as opposed to SULF2 supplied by the cancer cells." (PMID 36428645, 2022). "SULF2 is significantly higher in 16 cancer studies, of which 11 show >2-fold increase." (PMID 36428645, 2022). "Previous studies showed that SULF1 and SULF2 are upregulated in several cancers." (PMID 36428645, 2022). "Using qPCR, we found that the expression of SULF2 was significantly high in cancer tissues." (PMID 36612128, 2022). "Extracellular sulfatase 2 (SULF2), which belongs to the sulfatase family, selectively removes 6-O-sulfate groups from glucosamine residues within the heparan sulfate (HS) chains and modulates multiple molecular processes in the cancer microenvironment." (PMID 33889573, 2021). "According to the previous literature, SULF1 and SULF2 may have opposing effects in cancer progression despite similar structures and activities." (PMID 28525382, 2017). "The most thorough investigation of the role of SULF2 in cancer has been carried out by us in NSCLC." (PMID 26882224, 2016). "This preliminary analysis shows that SULF2 is present in saliva of some cancer patients but we cannot perform, at this time, a definitive assessment of SULF2 in mouthwash due to a lack of sufficient patient samples collected under standard optimized sampling conditions." (PMID 27223083, 2016).
cancer (continued). "To investigate whether SULF2 mediates the pro-invasive activity of IR in vivo, we utilized our previously established mouse model to compare the intravasation potential of cancer cells, a property that relies on their invasive activity." (PMID 26895473, 2016). "Moreover, the findings of this initial analysis open the possibility of blood SULF2 as a potential biomarker for early detection of cancer using a quantitative SULF2 ELISA." (PMID 26882224, 2016). "Also, we have performed preliminary analyses of SULF2 levels in blood from early stage NSCLC cancer patients." (PMID 26882224, 2016). "Therefore, we are providing the first validation of blood SULF2 as a potential biomarker for early detection of cancer using a quantitative ELISA." (PMID 26882224, 2016). "In considering Sulf1 or Sulf2 as drug targets, the main consideration is the increasing evidence implicating the Sulfs in cancer and whether these are responsible for augmenting cancer cell growth or inhibiting it." (PMID 25105093, 2014). "Similarly, comprehensive reviews on Sulf1 and Sulf2 provide further details of these enzymes in different cancer types." (PMID 25105093, 2014). "Although previous studies have demonstrated the involvement of SULF2 in cancer pathogenesis, its value for chemosensitivity prediction remains unclear." (PMID 24124496, 2013). "As the SULFs are established to promote Wnt/ß-catenin signaling in multiple developmental and cancer contexts, we sought to determine whether SULF2 regulates Wnt signaling in THCE cells." (PMID 23950901, 2013). "The cancer-promoting functions of SULF2 appear to work through activating Wnt signaling or releasing growth factors from the extracellular matrix, which may also have a pro-angiogenic effect." (PMID 20885998, 2010). "This supports our hypothesis that SULF1+ CAF alter the local microenvironment by creating invasive tracks through which the cancer cells migrate, while SULF2, originating from the cancer cells, promotes cancer cell growth more than it affects the local invasion." (PMID 41549062, 2026). "Indeed, SULF2 protein levels were elevated in LX-2 cells challenged in vitro with exogenous TGFβ1, with a strong and a highly significant correlation in gene expression between the two confirmed in the cancer genome atlas (TCGA) HCC dataset." (PMID 36589727, 2022). "Indeed, important roles for HSPGs and their modifying enzymes such as SULF2 are increasingly being recognized in various pathophysiological process, and have already been identified as potential therapeutic targets in diseases such as cancer." (PMID 33540508, 2021). "SULF2 was detected in 57% of tumors (n = 40) with a significant increase in intensity and number of stained cells compared to adjacent cancer-free tissue (p-value < 0.01), increasing with cancer stage when comparing stages 1 and 2 to stages 3 and 4 (p-value 0.01)." (PMID 27223083, 2016). "Finally, targeting SULF1 and/or SULF2 could be interesting strategies to develop novel cancer therapies." (PMID 21599997, 2011). "Targeting SULF1 and/or SULF2 could be interesting strategies to develop novel cancer therapies." (PMID 21599997, 2011). "It is also an abundant protein in the secretomes of all our HNSCC cancer and CAF cell lines which further supports our assumption that it interacts with Sulf-2 in vivo." (PMID 38825040, 2024). "Overall, our study shows that the Sulf-2 enzyme affects the crosstalk of CAF with HNSCC cells and the invasion of cancer cells into Matrigel." (PMID 37958342, 2023). "Our results show that Sulf-2 affects the growth and invasion of HNSCC spheroids and we demonstrated that HfFucCS inhibits not only the Sulf-2 enzymatic activity but also cancer cell invasion in the spheroid model." (PMID 37958342, 2023). "Pan-cancer analysis of TCGA and CPTAC (proteomics) data shows that SULF1 and SULF2 are oncogenic in a number of human malignancies and associated with poor survival outcomes." (PMID 36428645, 2022).
cancer (continued). "HNSC is an interesting case because SULF2 negatively affects the survival of stage III and IV patients while the impact of SULF1 is more prominent in stage I and II cancer patients." (PMID 36428645, 2022). "Among all the cancers examined, we observed the most consistent impact of SULF1 and SULF2 in PAAD and HNSC but other cancers are affected as well." (PMID 36428645, 2022). "This is uniformly corroborated by protein increases and at least six cancers (BRCA, HNSC, KIRC, LUSC, LUAD, PAAD) consistently upregulate both SULF1 and SULF2." (PMID 36428645, 2022). "We extended our analysis of HNSC by retrieving the RNA-seq data of 9160 patients in 32 cancer studies from the TCGA database to develop a systematic evaluation of SULF1 and SULF2 expression." (PMID 36428645, 2022). "Other cancers upregulate one of the SULFs (e.g., SULF1 in COAD) or the SULFs remain unchanged, but decreases, such as SULF2 in UCEC, are rare." (PMID 36428645, 2022). "Dysregulation of HSPG is frequently observed in cancer diseases, but we have insufficient knowledge of the function of HSPG and, in particular, SULF2 in the initiation and progression of HNSCC." (PMID 33585200, 2020). "And FLIP, FGF2, SULF2 and MMP13 are known to be overexpressed in various cancers and downstream of hnRNPK." (PMID 28423622, 2017). "Extracellular sulfatases, Sulfatase 2 (SULF2) and Sulfatase 1 (SULF1), have emerged as potential candidates for detection and therapeutic management of several cancers." (PMID 27223083, 2016). "DU-145 cancer cells transfected with SULF2 presented a 3-fold increase on migration through the membrane, and PC3 cancer cells transfected with SULF2 presented a 2-fold increase on migration." (PMID 25887999, 2015). "Transcriptional patterns of HS-metabolic enzymes (EXT1, EXT2, NDST1, NDST2, GLCE, 3OST1/HS3ST1, SULF1, SULF2, HPSE) were determined in normal, benign, and cancer human prostate tissues and cell lines (PNT2, LNCaP, PC3, DU145)." (PMID 24782989, 2014). "We also compared SULF2 among normal breast tissue, DCIS, and various grades of cancers." (PMID 40140347, 2025). "Studies from our and other laboratories have shown the upregulation of Sulf-2 in various cancer types and its negative impact on patient survival." (PMID 38825040, 2024). "SULF2 performs post-synthetic editing of 6-O-sulfation on heparan sulfate chains of HSPG which regulates binding of many ligands influencing the growth, metastasis, or immune evasion of cancers." (PMID 33585200, 2020). "Three enzymes – heparanase, Sulf1 and Sulf2 – play crucial roles in regulating HSPG functioning in this compartment and the up- and down-regulation of these proteins in a large variety of cancers demonstrates how important they are in promoting or repressing malignancy." (PMID 25105093, 2014). "Combinations of SULF2 inhibitors with chemotherapy may attenuate the cancer-initiating cell fraction, unlike chemotherapy alone." (PMID 40140347, 2025). "The sulfatase family, consisting of sulfatase 1 (SULF1) and sulfatase 2 (SULF2), is involved in multiple physiological and pathological processes by regulating the sulfation status of heparan sulfate proteoglycan, which has become one of the hot spots in cancer research (7, –9)." (PMID 32049100, 2020). "The five cancer free controls showed no SULF2 staining of the squamous epithelial cells." (PMID 27223083, 2016). "However as cancer is a multifactorial disease, the augmentation of SULF2 alone was not sufficient to produce these effects in normal prostate epithelial cells." (PMID 25887999, 2015).